EGFR (epidermal growth factor receptor)
Diseases named in the same sentence as EGFR in open-access papers (continued):
Sharing a sentence is not in itself a finding about the gene and the disease.
lung adenocarcinoma (continued). "We studied a series of consecutive lung adenocarcinoma from Caucasian non-smokers for which surgical frozen samples were available (n = 33) and showed that TWIST1 expression was linked to EGFR mutations (P<0.001), to low CDH1 expression (P<0.05) and low disease free survival (P = 0.044)." (PMID 22272264, 2012). "Therefore, in our calculations we assumed that 35% of never smokers with adenocarcinoma of the lung would be both EGFR and KRAS wild type." (PMID 22374459, 2012). "A signaling pathway involving EGFR, ErbB2, ErbB3, phosphatidylinositol 3-kinase (PI3K), Akt, glycogen synthase kinase 3- β (GSK3-β), and cyclin D1 is essential for the maintenance of survival, mitosis, and invasiveness of human lung adenocarcinoma cell lines as well as to evade apoptosis." (PMID 22724003, 2012). "In April 2004 just before the two initial major publications about activating mutations of epidermal growth factor receptor (EGFR) gene appeared, we examined a never smoker female with adenocarcinoma of the lung, and found a nine base pair deletion mutation in exon 19 of the EGFR gene." (PMID 19826477, 2009). "Our findings suggest that initial screening with diagnostic immunohistochemistry for lung adenocarcinomas, followed by targeted PCR-based assays for common HER2 exon 20 insertions in non-smoking patients with wild-type EGFR/ALK status, could represent a cost-effective algorithm." (PMID 40526089, 2025). "Our findings suggest that the EGFR mutation frequency was higher in women, non-smokers, lung adenocarcinoma, and the IA subtype in lung adenocarcinoma patients, while the KRAS mutation rate was higher in men and patients with longer tumor long diameter and lower in lung adenocarcinoma patients." (PMID 39364008, 2024). "However, as far as we know, whether this method can be applied to predict EGFR mutation status and prognosis based on multi-center 18F-FDG PET/CT in lung adenocarcinoma is not fully investigated." (PMID 37223682, 2023). "A high prevalence of EGFR and ALK mutations was found in the lung adenocarcinoma of non-smokers with better survivals, which may benefit from the invention of suitable target therapies, and suggested different oncogenic mechanisms of the cancer itself that call for further investigations." (PMID 35847783, 2022). "The results of this study demonstrate that ATM‐ and PIK3CA‐positive and EGFR‐negative mutation status are strongly associated with high levels of TMB and have the potential to be predictive biomarkers of response to immune checkpoint inhibitors in lung adenocarcinoma patients." (PMID 35521981, 2022). "To address this question, we retrospectively analyzed a cohort of 178 EGFR-mutant lung adenocarcinoma patients who had progressed on EGFR TKIs and received subsequent non-TKI systemic therapy to determine whether the addition of immunotherapy to chemotherapy truly improves clinical outcomes." (PMID 35884533, 2022). "To validate the SensiScreen® EGFR Liquid assays - c.2369C>T (p.T790M), exon 19 deletions, c.2573T>G/c.2573_2574TG>GT (p.L858R)—in the clinical setting, we used cfDNA extracted from blood of two retrospective cohorts including lung adenocarcinoma (AC) patients with or without metastases." (PMID 34166445, 2021). "Therefore, among the never-smoker lung adenocarcinoma cases without any known driver alterations in oncogenes such as EGFR, KRAS, ALK, etc., the estimated fraction of BCAR4 fusion could be approximately 2.2% (1/44)." (PMID 33204025, 2021). "However, under conditions of growth factor-deprivation that yield cells sensitive to EGF (epidermal growth factor), IL-35 can inhibit expression of PD-L1+ in the ADC (lung adenocarcinoma) tumor cell line without impacting EGFR (epidermal growth factor receptor)." (PMID 34093586, 2021). "Hence, it can be hypothesized that TKIs will have higher response rates in treating EGFR-mutant lung adenocarcinoma harboring VM, but data is lacking." (PMID 33549061, 2021).
lung adenocarcinoma (continued). "To this end, we overexpressed ERβ1 and ERβ5 in EGFR exon 19 deletion-harboring lung adenocarcinoma cells and assessed their ability to form heterodimers, as well as the relevance of ERβ1/ERβ5 heterodimerization in non-genomic signaling and response to EGFR TKIs." (PMID 33585221, 2020). "The Genetic Epidemiological Study of Lung Adenocarcinoma (GELAC) in Taiwan had found that the gene polymorphisms related to the estrogen biosynthesis and metabolism was associated with an increased occurrence of L858R mutation of the EGFR in non-smoking female lung adenocarcinoma patients." (PMID 28783064, 2017). "Moreover, an intriguing observation was the coexistence of FGFR1 true gene amplification and EGFR L858R mutation in a female, never smoker patient with lung adenocarcinoma, suggesting that some NSCLCs could be co-dependent on FGFR1 and EGFR for survival." (PMID 24736592, 2014). "Therefore, we considered that the diagnostic process of ALK rearrangement could be simplified as follows: screening by IHC with iAEP method followed by confirmatory FISH in EGFR and KRAS mutation-negative lung adenocarcinomas." (PMID 23936355, 2013). "Dose-response assays showed robust, dose-dependent growth inhibition in both EGFR-mutant (PC9) and KRAS-mutant (H358 and A549) lung adenocarcinoma cells, but not in the human bronchial epithelial cell line BEAS-2B." (PMID 41898563, 2026). "CT-guided biopsy confirmed stage IV lung adenocarcinoma (TTF-1 and Napsin A positive, PD-L1 TPS 80%, EGFR/ALK/ROS1 negative)." (PMID 42022515, 2026). "Lung adenocarcinoma (cT3N0M1c, AJCC 8th edition) with synchronous brain and pulmonary metastases molecularly characterized as epidermal growth factor receptor- and anaplastic lymphoma kinase-negative." (PMID 41517684, 2026). "The pathway between EGFR and MMP11 in lung adenocarcinoma has not been investigated yet, but there are some results on the pathway related to MMP11 in other tumors." (PMID 36756152, 2023). "In addition, the expression of c-myc, which is upregulated by LPCAT1 in patients with lung adenocarcinoma, was not enhanced compared with EGFR/PI3K in ESCC cells, which suggests that LPCAT1 may regulate cholesterol synthesis in ESCC cells primarily through these pathways." (PMID 34518524, 2021). "Moreover, since EGFR mutations are associated to other types of genetic polymorphism, some correlations between CA9 SNP and EGFR mutations that affect the presentation of lung adenocarcinoma may exist; so far, such research is absent." (PMID 32365566, 2020). "Lung adenocarcinoma cells were found to migrate towards anode independent of serum and EGFR (epidermal growth factor receptor)." (PMID 30186854, 2018). "In contrast, mice bearing a mutant human EGFR transgene, EGFRT790M-L485R, develop adenocarcinomas representative of lung adenocarcinomas occurring in non-smoker patients." (PMID 30060526, 2018). "The case of a 50-year-old male never smoker with stage IV Exon 19-del-EGFR mutant, ALK- and ROS-1-negative lung adenocarcinoma diagnosed in April 2015 was presented at the multidisciplinary tumor board." (PMID 28540256, 2017). "For example, EGFR and PTEN appear to be involved in the pathogenesis of lung adenocarcinoma, however the prevalence of both lesions is not well studied." (PMID 27484095, 2016). "Immunohistochemical staining of stage I lung adenocarcinoma tissues demonstrated a positive correlation between AURKA expression and phosphorylation of EGFR at Thr654 and Ser1046 in EGFR-mutant specimens, but not in EGFR-WT specimens." (PMID 23520446, 2013). "Unlike in lung adenocarcinoma (LUAD), clinical trials with epidermal growth factor receptor (EGFR) inhibitors showed no survival benefit for GBM and it remains unclear why." (PMID 39959305, 2025).
lung adenocarcinoma (continued). "The epidermal growth factor receptor (EGFR), among the first driver oncogenes identified in NSCLC, appears to be commonly altered in non-smoker patients with lung adenocarcinoma and represents a predictive biomarker for targeted therapy with EGFR-specific tyrosine kinase inhibitors (TKIs)." (PMID 40243603, 2025). "However, routine testing of advanced lung adenocarcinomas was not recommended until 2011, after the IPASS and EURTAC trials were published and oral EGFR‐TKIs such as erlotinib and gefitinib were approved for treatment of patients with EGFR mutations." (PMID 34921524, 2022). "Similarly, in lung adenocarcinomas occurring in non-smokers, RB1 inactivation through complex rearrangements was found in EGFR-mutant tumors and seemed to favor SCLC or squamous cell transformation." (PMID 33809148, 2021). "The comparison of mixed-IMA and pure-IMA showed that there was no statistical difference in the frequency of EGFR or ALK variations, suggesting that these gene-level changes might happen in the entire tumor when lung adenocarcinoma harbors mucinous components." (PMID 33505917, 2020). "Western blot analysis revealed the protein expression of epidermal growth factor receptor (EGFR) and pan-CK in Penl1 cells compared with HCC827 and H460 (lung adenocarcinoma cell lines; HCC827 was used as a positive control, and H460 was used as a negative control for EGFR-overexpression)." (PMID 27351128, 2016). "Despite promising preclinical data with neratinib (HKI-272; an irreversible ERBB inhibitor of EGFR and ERBB2) in the ERBB2-mutant NCI-H1781 cell line, clinical evaluation in patients with EGFR-driven lung adenocarcinomas does not support use of this inhibitor as a single agent." (PMID 23630663, 2013). "Epidermal growth factor receptor-targeted agents have also shown promise in the treatment of patients with bronchioalveolar carcinoma (BAC), which is considered to be a subtype of adenocarcinoma of the lung without pleural, stromal or vascular invasion (World Health Organization classification)." (PMID 14760365, 2004).
glioblastoma (2,260 papers, 1991 to 2026). The most malignant astrocytic tumor (WHO grade IV). "EGFRvIII is a tumor-specific, gain-of-function mutation of the EGFR gene that was first detected in 1990 in glioblastoma." (PMID 41821890, 2026). "EGFR gene amplification constitutes a diagnostic hallmark for glioblastoma, IDH-wildtype (GB, IDH-WT)." (PMID 41605133, 2026). "When EGFR is mutated in glioblastoma, it triggers a series of events that contribute to tumor growth, including proliferation, angiogenesis, differentiation, and cell survival." (PMID 41574218, 2026). "Epidermal growth factor receptor (EGFR) is amplified or mutated (EGFRvIII variant) in a large subset of glioblastomas, making it a prime target for ADC therapy." (PMID 40918539, 2025). "This gene encodes one of the most important markers of glioblastoma progression, second only to EGFR." (PMID 41009560, 2025). "An early-phase study of CARv3-TEAM-E T cell therapy demonstrated significant tumor regression in patients with glioblastoma, supporting EGFR (including the EGFR variant III and wild-type EGFR) as a promising immunotherapeutic target in glioblastoma." (PMID 41321637, 2025). "While wild-type EGFR is broadly expressed in normal tissues, EGFRvIII is a tumour-specific deletion variant found exclusively in glioblastoma and some other tumours." (PMID 40624498, 2025). "This process, recently described in glioblastoma, suggests the frequent occurrence and disappearance of EGFR mutations, contributing to temporal heterogeneity." (PMID 40197845, 2025). "For example, of fifty-five BoostDM driver mutations within EGFR in glioblastoma multiforme, nineteen had RNA VAF < 0.1, compared to only eleven with RNA VAF > 0.9." (PMID 40514689, 2025). "The mutual exclusivity of IDH1 and EGFR mutations suggests divergent oncogenic pathways, with IDH1 mutations predominantly associated with LGGs and EGFR mutations linked to more aggressive glioblastomas." (PMID 41425851, 2025). "The size of this cohort enabled us to elucidate rarer but significant molecular signatures, including 21q loss in glioblastoma as well as EGFR amplification and chromosome 22q loss in IDH1/2-mutant astrocytoma." (PMID 39164213, 2025). "For example, EGFRvIII (a truncated variant of EGFR) is a common amplification product in glioblastoma and is associated with increased tumor invasiveness." (PMID 41323387, 2025). "Genetic alterations in glioblastoma such as EGFR amplification are closely associated with tumor invasion and proliferation, presenting significant therapeutic targets." (PMID 40097417, 2025). "ZDHHC16-mediated SETD2 palmitoylation has been shown to promote DNA damage in EGFR-mutated glioblastoma." (PMID 40814339, 2025). "For example, more than half of patients with glioblastoma have tumors harboring alterations in the epidermal growth factor receptor (EGFR), such as amplification or mutation." (PMID 41497449, 2025). "Radio resistance is linked to EGFR mutations and amplifications in head and neck squamous cell carcinomas and glioblastoma (GBM)." (PMID 40248706, 2025). "Glioblastomas (GBMs) are lethal brain tumors in which EGFR gene amplification or mutation is frequently detected and is associated with poor prognosis." (PMID 39996727, 2025). "EGFRvIII, the most common EGFR mutation in glioblastoma with 25-30% prevalence, drives tumorigenesis through constitutive activation and promotes radioresistance by enhancing DNA repair capacity." (PMID 40386781, 2025).
glioblastoma (continued). "The mTOR (mechanistic target of rapamycin) pathway, which regulates oncogenic receptor tyrosine kinase (RTK) signaling, has been studied in glioblastoma (GBM) with EGFR mutations." (PMID 40867316, 2025). "The most common EGFR mutation in glioblastoma patients is the EGFR gene amplification, which occurs in about 40% of cases and is mainly found in primary glioblastomas." (PMID 40332381, 2025). "Previously, EGFR has been reported as an important driver gene in glioblastoma multiforme (GBM), associated with aggressive tumour growth and therapeutic resistance." (PMID 41292185, 2025). "Although our study focused on NF1 loss leading to Ras activation, RTKs, such as PDGFRA and EGFR, which are recurrently mutated in glioblastoma, can also activate Ras signaling through Ras GEFs such as SOS1." (PMID 40985888, 2025). "Key targets include the epidermal growth factor receptor (EGFR), which is often amplified or mutated in glioblastoma, and phosphatidylinositol 3-kinase (PI3K)/Akt/mTOR pathways, critical for cell proliferation and survival." (PMID 39796773, 2025). "A phase I clinical trial evaluated intrathecal administration of dual-target CAR-T cells directed against two glioblastoma-associated antigens: epidermal growth factor receptor (EGFR) and interleukin 13 receptor α2 (IL13Rα2)." (PMID 41301694, 2025). "EGFRvIII, a constitutively active mutation of epidermal growth factor receptor (EGFR) generated by an in-frame deletion of exons 2–7, is highly expressed in human glioblastoma and serves as a molecular hallmark of GBM." (PMID 40428395, 2025). "Epidermal growth factor receptor (EGFR) is the most frequently mutated receptor in glioblastoma (57% of cases), followed by platelet-derived growth factor receptor (PDGFRA) (13%), fibroblast growth factor receptor (FGFR) (3.2%), and c-MET (1.6%)." (PMID 40332381, 2025). "The EGFR pathway, often mutated or overexpressed in glioblastoma, plays a significant role in cell proliferation, survival, and invasion." (PMID 40650170, 2025). "Mutations in EGFR are the most common RTK aberrations in glioblastoma (GBM) and thus are an important therapeutic target." (PMID 40094009, 2025). "HIF-1α overexpression in gliomas is also driven by the activation of EGFR via the PI3K pathway, with EGFR gene amplification being a demonstrated hallmark of glioblastoma that contributes to gliomagenesis." (PMID 41034696, 2025). "EGFR (epidermal growth factor receptor) is frequently amplified (∼ 40 %) in glioblastomas and is associated with increased tumor aggressiveness." (PMID 41311621, 2025). "Preclinical data have demonstrated that osimertinib can reach high concentrations in the CNS and can be effective against EGFR mutated glioblastoma." (PMID 40094009, 2025). "Mechanistically, this combination remodels tumor-cell lipid metabolism and downregulates fatty acid synthesis genes in an NF-κB-dependent manner, highlighting a promising therapeutic strategy for EGFR-overexpressed or mutated glioblastoma." (PMID 41511341, 2025). "Around 50% of glioblastomas exhibit activating mutations, amplification, or overexpression of EGFR, leading to the activation of downstream PI3K/AKT/mTOR pathways." (PMID 39877641, 2025). "Several prognostic features were characterized, including NF1 alteration and 21q loss in glioblastoma, and EGFR amplification and 22q loss in IDH1/2-mutant astrocytoma." (PMID 39164213, 2025). "For example, glioblastoma patients treated with epidermal growth factor receptor (EGFR) variant III CAR-T cells showed reduced EGFRvIII expression in post-treatment biopsies." (PMID 40821802, 2025). "Because miR-221 expression is linked to EGFR activation in glioblastoma, we next examined miR-221 expression in HB-EGF and EGFR single KD or combined KD CRS cells." (PMID 39419989, 2024). "In primary glioblastomas, the presence of the active epidermal growth factor receptor (EGFR) vIII mutation is common, leading to a persistently active EGFR." (PMID 38339261, 2024).